APOA4 (apolipoprotein A4)
Diseases named in the same sentence as APOA4 in open-access papers (continued):
Sharing a sentence is not in itself a finding about the gene and the disease.
amyloidosis (25 papers, 2015 to 2026). A disorder characterized by the localized or diffuse accumulation of amyloid protein in various anatomic sites. "The causes of APOA4 amyloidosis are diverse, and further elucidation of the pathogenesis of APOA4 amyloidosis is expected in the future." (PMID 39699959, 2024). "In summary, we report that TFEB deficiency in the S3 segment of the proximal tubules of aged mice caused metabolic disorders and occasionally led to APOA4 amyloidosis." (PMID 39699959, 2024). "Compared with control young patients, nuclear TFEB localization in PTECs was reduced in the elderly patient withAPOA4 amyloidosis with a genetic variant of APOA4, which we previously reported." (PMID 39699959, 2024). "We found that TFEB deficiency in the proximal tubules caused metabolic disorders and occasionally led to apolipoprotein A4 (APOA4) amyloidosis." (PMID 39699959, 2024). "By confirming the presence of APOA4 amyloidosis, we demonstrated that the loss of TFEB in PTECs caused metabolic disorders in aged mice." (PMID 39699959, 2024). "Second, both increased hepatic APOA4 synthesis due to hepatic steatosis and decreased APOA4 degradation in TFEB-deficient PTECs are likely the presumptive mechanism of APOA4 amyloidosis." (PMID 39699959, 2024). "The patient with APOA4 amyloidosis, whose sample was used in this study and whose APOA4 sequence variants differ from those of other reports, showed amyloid deposition in the glomeruli and vessels of the renal cortex." (PMID 39699959, 2024). "This suggests that APOA4 and APOA2 are inextricably linked and that differentiating APOA4 amyloidosis from APOA2 amyloidosis is difficult." (PMID 39699959, 2024). "With age, decreased TFEB activity in proximal tubules causes systemic metabolic disorders and sometimes apolipoprotein A4-related amyloidosis through combined mitochondrial and lysosomal dysfunction." (PMID 39699959, 2024). "The result of LMD–LC-MS/MS analysis and these characteristics resemble those of mice with APOA4 amyloidosis in the absence of DREAM (Dp, Rb-like, E2F, and MuvB) assembly, indicating that APOA4 was the most likely cause of amyloidosis." (PMID 39699959, 2024). "TFEB downregulation in PTECs causes apolipoprotein A4 (APOA4) amyloidosis in aged mice." (PMID 39699959, 2024). "We demonstrated that TFEB deficiency in PTECs may cause APOA4 amyloidosis in aged mice." (PMID 39699959, 2024). "ASPs consisting of APOE, SAP, and APOA4 have been reported to be excellent surrogates for diagnosing amyloidosis when at least two were detected by LC-MS/MS." (PMID 41571866, 2026). "ApoAI and ApoAIV amyloidosis belong to rare amyloidosis types and contain APOA1 and APOA4 as amyloidogenic proteins, respectively." (PMID 40701201, 2025). "On the other hand, both the present study and previous reports showed that, in mice with APOA4 amyloidosis, amyloid fibrils were prominently deposited in the glomeruli." (PMID 39699959, 2024). "In patients with APOA4 amyloidosis, amyloid deposits are considered to be restricted to the renal medulla and to be absent in the glomeruli, interstitium, and vessels of the renal cortex." (PMID 39699959, 2024). "Recent studies reported that proteome profiles of amyloid deposits in individuals with APOA4 amyloidosis demonstrated the presence of APOA2 and vice versa." (PMID 39699959, 2024). "The clinical characteristics of patients with APOA4 amyloidosis include a gradual decline in renal function, infrequent proteinuria, and diagnosis in old age, and the medulla is the primary site of involvement." (PMID 39699959, 2024). "Supporting this result, we identified markedly decreased nuclear TFEB localization in the proximal tubules of elderly patients with APOA4 amyloidosis." (PMID 39699959, 2024). "As Apoa4 was identified as the main amyloidosis‐related protein in the deposits by LC–MS/MS, we confirmed the presence of this apolipoprotein by immunohistochemistry in the organs where the most massive amyloidosis was found." (PMID 29774542, 2018).
amyloidosis (continued). "In fact, there may be many patients with unidentified APOA4 amyloidosis, considering the findings of elevated plasma APOA4 concentrations in patients with CKD." (PMID 39699959, 2024). "Rather, genetic variants expanding the amyloidogenic hotspot may play a more crucial role in human APOA4 amyloidosis." (PMID 39699959, 2024). "However, we identified similar peptide regions in aged Tfebfl/fl KAP mice, the patient with APOA4 amyloidosis showing glomerular amyloid deposition, and Cotton-top tamarin with APOA4 amyloidosis." (PMID 39699959, 2024). "Furthermore, APOA4 amyloidosis that was reported in a species of monkey, the Cotton-top tamarin, also exhibited obvious glomerular deposition." (PMID 39699959, 2024). "Considering the results of in vivo and human autopsy samples, the age-related decrease in nuclear TFEB localization of PTECs may induce APOA4 amyloidosis in aged patients." (PMID 39699959, 2024). "Furthermore, we investigated the relationship between APOA4 amyloidosis and nuclear TFEB localization in PTECs using human autopsy samples." (PMID 39699959, 2024). "Any of these peptides could be signal sequences involved in APOA4 amyloidosis with glomerular deposition, and further studies on phenotypic differences are needed." (PMID 39699959, 2024). "However, the results of LMD–LC-MS/MS analysis and the tissue distribution of amyloid deposition are similar to those previously reported in APOA4 amyloidosis, and we conclude that APOA4 amyloidosis was the most likely type." (PMID 39699959, 2024). "To evaluate the applicability of this method in the study of amyloid genesis, we also investigated associated proteins that are frequently observed in amyloid deposition, such as serum amyloid P (SAP), apolipoprotein A4 (Apo A4), apolipoprotein E (Apo E), and vitronectin (VTN)." (PMID 36240260, 2022). "However, unlike aged Tfebfl/fl KAP mice, TFEB leaves some residual activity in elderly humans, which may contribute to the lower frequency of APOA4 amyloidosis in humans." (PMID 39699959, 2024). "Proteins such as clusterin, vitronectin, apolipoprotein E (ApoE), ApoA4, and serum amyloid P-component (SAP) constitute amyloid signature proteins found in all types of amyloidosis and across all affected tissues." (PMID 38892061, 2024). "As far as we know, three proteins named apolipoprotein E (APOE), apolipoprotein A-IV (APOA4), and serum amyloid P component (SAP) are usually accompanied with amyloid deposition in amyloidosis." (PMID 35418036, 2022). "All six ApoAIV samples displayed consistently high intensity ratios for the APOA4 protein, while other amyloidosis-relevant protein intensities were low or absent." (PMID 40701201, 2025). "The peptides identified in aged Tfebfl/fl KAP mice and this patient with APOA4 amyloidosis did not contain a signal sequence involved in amyloid seeds." (PMID 39699959, 2024). "Other diagnoses included ApoA4 amyloidosis (n = 2) and AA amyloidosis (n = 1), whereas amyloidosis was ruled out in 17 patients (20%)." (PMID 36551808, 2022). "Based on the fact that affected patients with amyloidosis also displayed hypotriglyceridemia and increased plasma levels of HDL-C as compared with non-carriers in the family, we next screened several candidate genes including the APOC3, APOC1, APOC2, APOC4, APOA4, APOA5 and APOE genes." (PMID 26790392, 2016). "Additional “peaks”, primarily among the amyloid signature proteins APOA4, APOE and VTN have been reported before, but should not be misinterpreted as indicative of mixed amyloidosis." (PMID 40701201, 2025). "We were able to additionally type three samples of ALλ (CON7; lymph node (n = 1)), ATTR (CON8; bursa (n = 1)), and ALκ (CON9; myocardium (n = 1)) with unspecific or negative IHC results, but additional high abundance of ApoA4, FGA, and KRT, respectively, without defining the amyloidosis type." (PMID 40701201, 2025).
chronic kidney disease (17 papers, 2012 to 2025). Impairment of the renal function secondary to chronic kidney damage persisting for three or more months. "Apolipoprotein A4 (ApoA-IV), which is known to have anti-atherogenic properties, is also known to be elevated in patients with chronic kidney disease." (PMID 40397923, 2025). "The high expression level of apoA4 have also been observed in diabetic or chronic kidney disease patients with renal function declined faster." (PMID 37033921, 2023). "APOA4 is elevated in patients with chronic kidney disease, and APOA1 in diabetic rat bladders." (PMID 25915536, 2015). "In contrast, APOA4 concentrations are markedly increased in chronic kidney disease (CKD), mainly in dialysis patients, resulting in a potential early marker of renal impairment that can predict CKD progression." (PMID 40427671, 2025). "Elevated plasma levels of ApoA4 have been shown to predict progression of chronic kidney disease in nondiabetic patients and the progression of renal impairment in T2D." (PMID 32830851, 2020).
Hepatic steatosis (17 papers, 2012 to 2025). Steatosis is a term used to denote lipid accumulation within hepatocytes. "To explore the pathogenic mechanisms underlying ApoA4 regulation of liver steatosis through liver immune cells, we performed scRNA-seq to profile the reprogramming of the liver immune microenvironment from the two groups of mice." (PMID 36426356, 2022). "Therefore, increased abundance of 0-Gran-Wfdc17, elevated levels of neutrophil serine proteases (NE, PRTN3 and Cathepsin G), and upregulated genes enriched in NETs formation are involved in the aggravation of fatty liver caused by loss of ApoA4." (PMID 36426356, 2022). "ApoA4 is reported to counter diet-induced hepatic steatosis, and its immediate activity in livers of HGI fed-animals indicates detrimental effects even in short-term exposures." (PMID 38333717, 2024). "It was reported that hepatic steatosis was more pronounced in ApoA4 knockout rats and mice than wildtype control." (PMID 36426356, 2022). "The previous report has also indicated that hepatic steatosis would stimulate hepatic ApoA4 expression, which in turn would reduce the hepatic lipid burden by promoting lipoprotein particle expansion." (PMID 29179490, 2017). "In addition to intestinal lipid metabolism, ApoA4 has been shown to play roles in food intake and glucose homeostasis and even plays a role in restricting hepatic steatosis." (PMID 40158856, 2025). "In mice, hepatic steatosis induces APOA4 expression, which reduces the lipid burden." (PMID 39699959, 2024). "The expression of APOA4-AS and Apoa4 in the liver of human fatty liver patients and ob/ob mice showed a tendency to increase, and inhibiting APOA4-AS could significantly reduce the content of TG and TC in the blood of ob/ob mice." (PMID 36970373, 2023). "However, the effect of ApoA4 on liver immune cells and the precise immune cell subsets that exacerbate fatty liver remain elusive." (PMID 36426356, 2022). "Meanwhile, some evidence showed that ApoA4 protein expression could be stimulated by hepatic steatosis." (PMID 29179490, 2017). "Moreover, supplementation was able to downregulate genes, such as CIDEA (cell death-inducing DFFA-like effector A) and Apoa4 (apolipoprotein A-IV), which are known to be related to hepatic steatosis and inflammation." (PMID 28587078, 2017). "Lipoproteins are composed of lipids, cholesterol and apolipoproteins, and the expression of apolipoproteins A1, A4 and C3 (APOA1, APOA4 and APOC3) increased significantly in the hepatic steatosis groups, suggesting an increased level of cholesterol transport." (PMID 37568219, 2023). "Deleting FGF21 from LSD1-LKO liver partially reversed the improved hepatic steatosis, likely due to the FGF21-dependent alteration of lipid uptake (Cd36) and secretion (ApoB, ApoA4, and ApoA5)." (PMID 34314389, 2021). "After founding the restriction of ApoA4 on diet-induced hepatic steatosis via SREBF1-mediated lipogenesis, meanwhile, we hypothesized that regulation of ApoA4 on hepatic immune cells involved in the pathogenesis of NAFL." (PMID 36426356, 2022). "The expression levels of ACSL5, APOA4 and ME1 in F0 chickens with fatty liver were higher than those in chickens without fatty liver (p < 0.05), but the differences were highly significant in the F1 generation (p < 0.01)." (PMID 29642504, 2018).
dyslipidemia (14 papers, 2008 to 2024). "Genome-wide association studies have revealed that an APOA4 single nucleotide polymorphism (SNP), rs5104, is associated with dyslipidemia in Han Chinese and with triglycerides in response to lipid-lowering treatment drug, fenofibrate." (PMID 34168225, 2021). "In contrast, the APOA5 -12,238C (p = 0.01) and the APOA4 Ser347 (p = 0.04) alleles were associated with a lower risk of metabolic syndrome." (PMID 18789138, 2008). "Overall, this suggests that APOA5 and APOA4 genetic variability affected susceptibility to metabolic syndrome." (PMID 18789138, 2008). "Changes in Apoa4 expression can be associated with dyslipidemia and increased cardiovascular risk." (PMID 39479684, 2024). "Given the epidemic proportions of metabolic syndrome and the notion that mitigating comorbidities that might increase one’s risk for worse outcomes, the need to better understand how APOA4 acts on different tissues at the molecular level is paramount." (PMID 34168225, 2021). "The other haplotype (CCTTC, carrying the APOA5 12,238C, the APOA4 Ser347 and the APOC3 -482T alleles) was associated with a 26% reduction in metabolic syndrome risk (p = 0.03)." (PMID 18789138, 2008). "The APOA5 Trp19 allele increased the odds ratio for metabolic syndrome, whereas the APOA5 -12,238C and APOA4 Ser347 alleles decreased it." (PMID 18789138, 2008). "Similarly, variants in the 11223.3 chromosomal region involving APOA1, APOA4, APOA5, and APOC loci were reported to be strongly influencing the lipid levels and dyslipidemia in studies from northern and southern India." (PMID 38348409, 2023). "Secondly, adjustment for triglycerides (but not for other metabolic syndrome-related criteria) abolished the associations between APOA5 or APOA4 SNPs and the risk of metabolic syndrome." (PMID 18789138, 2008). "Compared with homozygotes for the common allele, the odds ratio (OR) [95% CI] for metabolic syndrome was 1.30 [1.03–1.66] (p = 0.03) for APOA5 Trp19 carriers, 0.81 [0.69–0.95] (p = 0.01) for APOA5 -12,238C carriers and 0.84 [0.70–0.99] (p = 0.04) for APOA4 Ser347 carriers." (PMID 18789138, 2008). "The decreased risk of metabolic syndrome observed in APOA5 -12,238C and APOA4 Ser347 carriers merely reflected the fact that the APOA5 Trp19 allele was in negative linkage disequilibrium with the common alleles of APOA5 -12,238T>C and APOA4 Thr347Ser polymorphisms." (PMID 18789138, 2008). "Furthermore, the APOA5 -12,238C and APOA4 Ser347 alleles were associated with a lower risk of metabolic syndrome – possibly due to their negative linkage disequilibrium with the APOA5 Trp19 allele." (PMID 18789138, 2008). "The reduced risk of metabolic syndrome observed in carriers of APOA5 -12,238C and APOA4 Ser347 alleles merely reflected the negative linkage disequilibrium existing between these alleles and the APOA5 Trp19 allele." (PMID 18789138, 2008).
ovarian carcinoma (12 papers, 2011 to 2024). A malignant neoplasm originating from the surface ovarian epithelium. "The loss of APOA1, APOA2, and APOA4 was reported in ovarian cancer patients." (PMID 38067270, 2023). "Thus, reduced CNDP1 levels have been reported in different aggressive cancer forms while APOA4 has been shown to be increased in pediatric forms of high risk acute leukemia but lower in adult women with ovarian cancer." (PMID 25898255, 2015). "A panel composed of three proteins (FGG, MUC16, and APOA4) in serum sEVs showed remarkable performance for ovarian cancer screening in populations." (PMID 35954383, 2022). "Through univariate and multivariate logistic regression analyses, a novel model comprising three proteins (fibrinogen gamma gene (FGG), mucin 16 (MUC16), and apolipoprotein (APOA4)) was established to screen patients with ovarian cancer." (PMID 35954383, 2022). "al. also measured decreased plasma concentrations of Afamin and APOA4 in patients with ovarian cancer, with APOA4 adding independent diagnostic information to CA125 and age for differentiating ovarian cancer from benign and healthy samples." (PMID 25265318, 2014). "APOA4 protein itself was already identified as an up-regulated biomarker for ovarian cancer, whereas this was also known to be regulated by nutritional and metabolic stress." (PMID 21533267, 2011). "It was reported that APOA4 was decreased in the serum small extracellular vesicles of ovarian cancer patients, which implies that the relationships between APOA4 and tumor progression may be different among various cancer types." (PMID 38584705, 2024). "The serum level of APOA4 was noted to be reduced in the serum of patients with ovarian cancer." (PMID 38067270, 2023). "Apolipoprotein A IV (APOA4) and vitamin D binding protein (VDBP) significantly discriminated malignant from benign cases of ovarian cancer but was not as good as CA125 for diagnostic accuracy." (PMID 30598658, 2018). "Indeed the best candidate markers for differential diagnosis of ovarian cancer identified here fell into these functional categories, including proteins A1AT, APOA4, and VDBP that were selected for further evaluation as ovarian cancer biomarkers." (PMID 25290619, 2014).
coronary artery disease (11 papers, 2006 to 2025). "Human studies have identified polymorphisms in the APOA4 gene that associate with its plasma levels, inter-individual variability in cholesterol levels, and risk of coronary heart disease." (PMID 39335631, 2024). "Human studies have identified polymorphisms in the ApoA4 gene that associate with ApoA4 plasma levels, inter-individual variability in cholesterol levels, and risk of coronary heart disease." (PMID 16584536, 2006). "A low plasma ApoA-4 level is associated with coronary artery disease in type 1 DM." (PMID 36619946, 2022). "In clinical studies, a low concentration of plasma APOA4 is associated with coronary artery disease, and this association is independent of HDL-C and triglyceride concentrations." (PMID 34634315, 2021).
type 2 diabetes (11 papers, 2009 to 2025). "Therefore, apoA4, the only upregulated protein in the risk allele carriers in our research, might have an association with type 2 diabetes through the interaction with NOS1AP (or nNOS)." (PMID 23671866, 2013). "Clinical studies showed that IGFBP-3 is down-regulated in Type 2 Diabetes patients with renal disfunction, and predict future renal decline in people with type 2 diabetes combined with apoA4 and CD5L." (PMID 35002740, 2021). "Recently, of eight candidate biomarkers studied after adjustment for clinical predictors, apolipoprotein A4 (ApoA4), CD5 antigen-like (CD5L), and complement C1q subcomponent subunit B (C1QB) independently predicted rapid decline in eGFR in 345 people with type 2 diabetes." (PMID 29520581, 2018).